LCDR (lysosome cell death regulator)
Synonyms: LINC00653
Gene: Long non-coding RNA gene on chromosome 20 (18,794,078 to 18,796,067, forward strand). Ensembl gene ENSG00000273148.
Diseases named in the same sentence as LCDR in open-access papers:
LCDR is named in the same sentence as 1 disease in open-access papers, as found by Europe PMC text mining. Sharing a sentence is not in itself a finding about the gene and the disease.
LCDR shares sentences with these, for which no sentence is quoted: cancer (1 paper).